TCF3 (transcription factor 3)
Diseases named in the same sentence as TCF3 in open-access papers (continued):
Sharing a sentence is not in itself a finding about the gene and the disease.
myeloma (6 papers, 2016 to 2023). "Taken together, these results show increased dependency on the B cell lineage-specific transcription factors in blood cancers, with cancer-type-specific addiction to TCF3/IRF4 regulatory pathway in myeloma mediated by MYC expression." (PMID 35382456, 2022). "Dependencies on POU2AF1 and PIM2, the target genes of TCF3 and IRF4 transcription factors, suggest cancer-type-specific addiction to transcriptional regulatory pathway in myeloma." (PMID 35382456, 2022). "TCF3 and IRF4 have previously been suggested as dependencies in myeloma and are part of the core regulatory circuitry, promoting tumorigenesis in cooperation with aberrant MYC activity." (PMID 35382456, 2022). "Furthermore, we found downregulation of SDC1 and TCF3 and upregulation of DDIT3 in the myeloma cluster, consistent with the observations in MM cell lines." (PMID 36631435, 2023). "Interestingly, we only discovered a small network of proteins consistent across all eight myeloma subgroups, highlighted by the over-expression of STAT1, TCF3 and interferon alpha." (PMID 33572851, 2021). "Given that TCF3 activates numerous proapoptotic genes, it is conceivable that tumor-suppressor effect does not depend on a single factor but develops as a “death by a thousand cuts” as it was supposed for IRF4 depletion in multiple myeloma." (PMID 27166193, 2016).
neuroblastoma (6 papers, 2016 to 2025). Neuroblastoma (NB) is the most common solid, extracranial childhood tumor. "We next assessed the association of HNRNPH1 abundance with TCF3 transcript variant ratios in neuroblastoma in further detail." (PMID 40766465, 2025). "In our study, we observed that neuroblastomas exhibit one of the greatest imbalances in the expression of TCF3 transcripts variants, with TCF3-exon 18a transcripts dominating and that this tumor type also expresses slightly higher levels of HNRNPH1 than other solid tumor types." (PMID 40766465, 2025). "Extending this finding, we present evidence that in neuroblastoma, HNRNPH1 is a MYCN target, potentially explaining the higher levels of HNRNPH1 and TCF3-exon 18a transcript variants in this tumor type." (PMID 40766465, 2025). "In neuroblastoma, TCF3 shows increased expression in MYCN amplified tumors, and its increased expression is linked to poor prognosis." (PMID 33466745, 2021). "For example, testicular germ cell tumors (TGCT) and neuroblastoma (NB) exhibit greater inclusion of TCF3-exon 18a than exon 18b, and pheochromocytoma and paragangliomas (PCPG) and adrenocortical carcinomas (ACC) exhibit the greater inclusion of TCF3-exon 18b than exon 18a." (PMID 40766465, 2025). "We have interrogated in silicopublic neuroblastoma databases for regulators involved in the RB-E2F pathway especially for E2F factors themselves, and we identified the E2F transcription factor 3 (E2F3) expression as a potential prognostic marker in stage 4S neuroblastoma." (PMID 32429447, 2020).
T cell lymphoma (6 papers, 2011 to 2025). "BIK has also been reported to be upregulated upon over-expression of E47 in T cell lymphoma and in a murine TCF3/E2A-deficient hematopoietic progenitor cell line." (PMID 27166193, 2016). "Both T cell-specific Id1 expression and Tcf3 ablation lead to T cell lymphoma formation in transgenic mice at high frequencies, while Id1 gene disruption can partially rescue the survival of Tcf3-null mice." (PMID 41146039, 2025). "In T cell lymphomas TCF3 exerts its tumor suppressing function by repression of proto-oncogenes MYC, CDK6 and by up-regulation of cell cycling inhibitor CDKN1A/p21, thereby leading to cell cycle arrest." (PMID 27166193, 2016). "TF TCF3 (E2A) is involved in T-cell human leukemias, and Tcf3 KO develops T-cell lymphoma." (PMID 28401061, 2017). "Similarly to cHL, in T cell lymphomas, ID proteins including ID2, block lymphocyte differentiation and promote T-cell lymphomagenesis by antagonizing TCF3." (PMID 27166193, 2016). "In regard to molecular mechanisms of TCF3 antitumor effects, in Sézary syndrome (a subtype of T cell lymphoma) derived cells, no significant cell death induction was observed after E47 overexpression, whereas, up-regulation of proapoptotic genes including BCL2L11 and BIK have been seen." (PMID 27166193, 2016).
acute myeloid leukemia (5 papers, 2010 to 2026). Acute myeloid leukemia (AML) is a group of neoplasms arising from precursor cells committed to the myeloid cell-line differentiation. "Although it was difficult to validate which TF can directly bind the PRE1 SNP due to insufficient ChIP-seq data in T/NK cells, we found the PRE1 candidate SNP rs11227311 to be located within a weak TCF3 ChIP-seq peak in Kasumi1 acute myeloid leukemia cell line [GEO GSE43834]." (PMID 31507631, 2019).
B cell lymphomas (5 papers, 2013 to 2021). "We have shown that the BIK expression significantly correlated with TCF3 in normal B cell subtypes and B cell lymphomas." (PMID 27166193, 2016).
melanoma (5 papers, 2020 to 2025). A malignant, usually aggressive tumor composed of atypical, neoplastic melanocytes. "Elevated expression of TCF3 was linked to better outcomes in the overall cohort (HR = 0.75,P = 0.00068) and in bladder cancer (HR = 0.49,P = 0.018) and urothelial cancer (HR = 0.76,P = 0.056) patients, while glioblastoma (HR = 12.22,P < 0.001) and melanoma (HR = 1.38,P = 0.048) were the opposite." (PMID 39205642, 2024). "The investigation revealed that SUZ12, SOX2, TCF3, NANOG and SMAD4 are the maximum chief TFs that control the largest number of genes associated with metastatic-melanoma." (PMID 39820173, 2025). "Activated transcription factor 3 (ATF3) expression is induced by β-catenin in melanoma cells, which suppresses C-C motif chemokine ligand 4 (CCL4) gene transcription." (PMID 36232859, 2022). "Five hub genes including CXCL11, ICAM1, LEF1, MITF, and STAT1 were identified, SUZ12, SOX2, TCF3, NANOG, and SMAD4 were determined as the most significant TFs in metastatic-melanoma." (PMID 39820173, 2025).
B-cell precursor acute lymphoblastic leukemia (4 papers, 2012 to 2021). "Previous analyses of this gene have linked differential methylation patterns to higher birth weight-for-gestational age and a translocational rearrangement of this gene and TCF3/E2A has been associated with B-cell acute lymphoblastic leukaemia." (PMID 33933144, 2021). "TCF3 (M31523) is involved in 19p13 chromosome rearrangement and acts as a tumor suppressor gene in B-cell precursor acute lymphoblastic leukemia." (PMID 22830977, 2012).
diabetes (4 papers, 2015 to 2024). "TCF3 is highly expressed in islets of T2D patients and is associated with Wnt signaling in diabetes pathogenesis; and VSX1, expressed in ocular tissues, is associated with eye diseases." (PMID 25898945, 2015). "Therefore, our findings and existing published evidences can lead to the hypothesis that mutations in the CNTN4 gene modify its binding with TCF3 in the pancreas and VSX1 in the brain and activate related genetic regulations for diabetes and its complications." (PMID 25898945, 2015).
embryonal carcinoma (4 papers, 2013 to 2022). A non-seminomatous malignant germ cell tumor characterized by the presence of large germ cells with abundant cytoplasm resembling epithelial cells, geographic necrosis, high mitotic activity, and pseudoglandular and pseudopapillary structures formation. "IHC analysis of Oct4 also showed that Tcf3−/− teratomas are largely composed of undifferentiated, embryonic carcinoma (EC) -like cells, confirming their undifferentiated nature." (PMID 23658527, 2013). "In cancer, TCF3 inhibits embryonal carcinoma malignancy by regulating Oct4 expression." (PMID 29299140, 2017).
endometrial cancer (4 papers, 2015 to 2025). Primary or metastatic malignant neoplasm involving the endometrium (mucous membrane that lines the endometrial cavity). "In this study, we demonstrated that TCF3 is epigenetically silenced by EZH2 and DNMT3B and functions as a tumor suppressor in endometrial cancer." (PMID 34175897, 2021).
glioblastoma (4 papers, 2013 to 2024). The most malignant astrocytic tumor (WHO grade IV). "In glioblastoma, downregulation of TCF3 by ASCL1 is essential for the maintenance and in vivo tumorigenicity of glioblastoma CSCs." (PMID 29299140, 2017).
hepatocellular carcinoma (4 papers, 2013 to 2023). A malignant tumor that arises from hepatocytes. "More recently, METTL13 has been shown as a crucial mediator of HN1L (hematological and neurological expressed 1-like) in modulating hepatocellular carcinoma (HCC) cell growth and metastasis via co-activating TCF3 (transcription factor 3) and ZEB1 (zinc finger E-box binding homeobox 1) expression." (PMID 35925508, 2023). "In addition, one study of four genes [E‐cadherin, MMP9 (matrix metalloproteinase‐9), TCF3 (transcription factor 3)/E47 and ID2 (inhibitor of differentiation 2)] has validated their prognostic value, in terms of overall survival, in a large cohort of hepatocellular carcinomas (HCC)." (PMID 28590039, 2017).
Immunodeficiency (4 papers, 2022 to 2025). Failure of the immune system to protect the body adequately from infection, due to the absence or insufficiency of some component process or substance. "Recent next-generation sequencing studies on the pathogenesis of BL have revealed that mutations in the transcription factor TCF3 or its negative regulator ID3 occurred in approximately 70% of sporadic and immunodeficiency-related BL cases and 40% of endemic BL cases." (PMID 36001860, 2022).
Obesity (4 papers, 2015 to 2022). Accumulation of substantial excess body fat. "Thus, studies on pathways downstream of TCF3 may pave the path for better understanding the mechanism underlying associations of FTO with obesity." (PMID 25647475, 2015).
systemic lupus erythematosus (4 papers, 2017 to 2024). An autoimmune multi-organ disease typically associated with vasculopathy and autoantibody production. "In this family, the synergistic interaction of TNFRSF13B/TACI and TCF3 mutations resulted in a severe immunodeficiency and systemic lupus erythematosus (SLE) in the proband." (PMID 30323807, 2018). "A patient with a TCF3 HI variant and a heterozygous TNFRSF13B variant was diagnosed with severe CVID and systemic lupus erythematosus affected by epistasis." (PMID 39073655, 2024).
liver cancer (3 papers, 2017 to 2024). An epithelial or non-epithelial malignant neoplasm that arises from the liver. "TCF3, with significantly elevated expression in tumor tissues, promotes cancer cell proliferation by regulating the cell cycle in liver cancer." (PMID 38255993, 2024). "Collectively, this study reveals the miR-449a–TCF3-Nanog axis as a potential therapeutic target for liver cancer." (PMID 29299140, 2017). "Furthermore, miR-449a expression was negatively correlated with TCF3 expression and positively correlated with Nanog expression in liver cancer tissues." (PMID 29299140, 2017). "In addition, we demonstrated that Nanogpos liver cancer cells have low expression of TCF3." (PMID 29299140, 2017). "Last but not least, TCF3 is one of the components in Wnt/β-catenin signaling pathway, which plays important role in activating liver cancer stem cells." (PMID 28158312, 2017).
ovarian carcinoma (3 papers, 2011 to 2022). A malignant neoplasm originating from the surface ovarian epithelium. "Recent findings demonstrated that e2f transcription factor 3, a key cell cycle protein, was regulated by miR-210 and that high frequency of miR-210 gene copy deletions were found in ovarian cancer patients." (PMID 21738599, 2011).
triple-negative breast carcinoma (3 papers, 2023 to 2025). An invasive breast carcinoma which is negative for expression of estrogen receptor (ER), progesterone receptor (PR), and human epidermal growth factor receptor 2 (HER2). "TCF3 enhances cell proliferation and invasion in triple-negative breast cancer by activating transcription." (PMID 40610429, 2025).
bladder cancer (2 papers, 2024 to 2025). "These efforts will provide a foundation for developing TCF3-targeted therapies and improving prognostic stratification in bladder cancer patients." (PMID 40610429, 2025). "In conclusion, our study unveils that TCF3 is significantly overexpressed in bladder cancer, suggesting its role in accelerating bladder cancer advancement by interacting with TMBIM6." (PMID 40610429, 2025). "Our findings demonstrate that TCF3 facilitates bladder cancer progression through the enhancement of TMBIM6-Ca2+-mediated ferroptosis resistance." (PMID 40610429, 2025). "To investigate the potential variation of TCF3 expression in bladder cancer, we analyzed TCF3 expression in both control and cancerous tissues within the TCGA database." (PMID 40610429, 2025). "The application of Erastin reversed these effects, indicating that TCF3 facilitated the progression of bladder cancer cells by promoting resistance to ferroptosis." (PMID 40610429, 2025). "The identification of TCF3 as a key regulator in bladder cancer represents a significant advancement in understanding tumor biology and Ca2+-dependent ferroptosis-mediated treatment resistance." (PMID 40610429, 2025). "In summary, our research demonstrates that TCF3 promotes the development of bladder cancer by inducing Ca2+-dependent ferroptosis resistance through its interaction with TMBIM6." (PMID 40610429, 2025). "These insights position TCF3 as a promising candidate for targeted therapy, particularly in bladder cancer, where therapeutic options remain limited." (PMID 40610429, 2025). "To further investigate whether TCF3 modulates bladder cancer cell function through ferroptosis, we overexpressed TCF3 in bladder cancer cells and treated them with Erastin." (PMID 40610429, 2025). "Our study found that TCF3 expression was significantly upregulated in bladder cancer cells." (PMID 40610429, 2025). "To further explore the impact of TCF3 on bladder cancer development by influencing intracellular Ca2+ concentration and ferroptosis, we treated the cells with BAPTA-AM in combination with sh-TCF3." (PMID 40610429, 2025). "Both TCF3 and TMBIM6 emerge as promising biomarkers and therapeutic targets for bladder cancer intervention." (PMID 40610429, 2025). "Our findings demonstrate that TCF3 directly interacts with TMBIM6 and transcriptionally upregulates its expression, thereby mediating Ca2+-dependent ferroptosis resistance and facilitating bladder cancer progression." (PMID 40610429, 2025). "TCF3 and TMBIM6 emerge as promising biomarkers and therapeutic targets for bladder cancer." (PMID 40610429, 2025).
clear cell renal cell carcinoma (2 papers, 2020). "In human clear cell renal cell carcinoma, it has been shown that the expression of E-cadherin and HIF-1α was mutually exclusive due to HIF-1α-mediated induction of TCF3, ZFHX1A, and ZFHX1B, which repress E-cadherin gene transcription." (PMID 32733884, 2020). "Moreover, it has been reported that HIF-1 promotes EMT of carcinoma cells in clear cell renal cell carcinoma, suppressing E-cadherin indirectly by inducing the expression of ZEB1 and ZEB2 and E2A immunoglobulin enhancer-binding factors E12/E47 (TCF3)." (PMID 32625096, 2020).
diffuse large B-cell lymphoma (2 papers, 2016 to 2025). "We also showed that differential methylation of genes bound by TCF3, the human ortholog of E2a, is associated with treatment failure in diffuse large B-cell lymphoma patients." (PMID 27146673, 2016). "In contrast, NKX6-3 is highly expressed in TCF3-subtype BCP-ALL and GC-B-cell-derived diffuse large B-cell lymphoma subsets, contrastingly indicating oncogene activity in developing B-cells." (PMID 41153416, 2025).
esophageal squamous cell carcinoma (2 papers, 2023 to 2024). Esophageal squamous cell carcinoma (ESCC) is a type of esophageal carcinoma (EC) that can affect any part of the esophagus, but is usually located in the upper or middle third. "The results above suggested that TCF3 affected the stemness of esophageal squamous cell carcinoma by regulating ID1." (PMID 37607071, 2023). "We wanted to explore the relationship between transcription factors and stemness, so we tested the related genes using TCGA database and found that TCF3 had higher expression in esophageal squamous cell carcinoma." (PMID 37607071, 2023). "In the CCK8 assay, the proliferation ability of esophageal squamous cell carcinoma cells was reduced after TCF3 knockdown." (PMID 37607071, 2023). "Interestingly, the expression of TCF3 was higher in esophageal squamous cell carcinoma, rectum adenocarcinoma, and stomach adenocarcinoma tissues than in normal tissues." (PMID 39205642, 2024). "However, the effect of TCF3 in the progression of esophageal squamous cell carcinoma (ESCC) is poorly known." (PMID 37607071, 2023).
germ cell tumor (2 papers, 2010 to 2025). A benign or malignant, gonadal or extragonadal neoplasm that originates from germ cells. "Absence of octamer binding transcription factor 3/4, α-fetoprotein and CD-30 staining helps in exclusion of most germ cell tumors." (PMID 21108779, 2010).
head and neck squamous cell carcinoma (2 papers, 2023 to 2024). A squamous cell carcinoma that arises from any of the following anatomic sites: lip and oral cavity, nasal cavity, paranasal sinuses, pharynx, larynx, and salivary glands. "In reviewing the literature on Head and Neck Squamous Cell Carcinoma (HNSCC), the overexpression of MMP-9 upregulated by Galectin-7 interacting with TCF3 might significantly promote lymph node metastasis." (PMID 37600570, 2023).
lung adenocarcinoma (2 papers, 2016 to 2020). A carcinoma that arises from the lung and is characterized by the presence of malignant glandular epithelial cells. "TCF3 turns out to be confirmed to contribute to lung adenocarcinoma on methylation alteration." (PMID 27412431, 2016). "As for the microRNA level, the interactions between TCF3 and a group of microRNAs (miR-590, miR-17 and miR-18) has been confirmed, validating that TCF3 may also contribute to the initiation and progression of lung adenocarcinoma on such level." (PMID 27412431, 2016). "The methylation alteration of TCF3 has been confirmed to contribute to the proliferation of A549 cells, a typical lung adenocarcinoma cell line in vitro experiments, implying that such gene may also contribute to the initiation and progression of lung adenocarcinoma on such level." (PMID 27412431, 2016).
lung fibrosis (2 papers, 2024). "Recent findings indicate that activating transcription factor 3 (ATF3) can stimulate LINC00941/lncIAPF to promote the differentiation of fibroblasts into myoblasts by inhibiting ELAVL1/HuR-dependent autophagy in pulmonary fibrosis." (PMID 39612365, 2024). "However, the implication of TCF3 in lung fibrosis is still unknown." (PMID 38529638, 2024).
osteosarcoma (2 papers, 2020 to 2022). A usually aggressive malignant bone-forming mesenchymal neoplasm, predominantly affecting adolescents and young adults. "Four other TF were also found with a high number of connections and appear to be associated with osteosarcoma (EWSR1-FLI1 and NFIC), cranium formation (TCF3), soft tissue calcification and chondrocyte differentiation (NF-KAPPAB)." (PMID 32493207, 2020).
ovarian endometriosis (2 papers, 2021 to 2024). A non-neoplastic disorder characterized by the growth of endometrial tissue in the ovaries. "As a potent E-cadherin repressor, TCF-3 activates SNAIL transcription by coupling with β-catenin in ovarian endometriosis, and the over-expression of TCF3 induces EMT and fibrosis in human renal proximal tubular epithelial cells." (PMID 38529638, 2024). "It has been reported that β-catenin/transcription factor 3 can bind to the Snail promoter and activate its transcription, thus playing a key role in β-estradiol-mediated EMT during the development of ovarian endometriosis." (PMID 34093834, 2021).